SOX11 (SRY-box transcription factor 11)
Diseases named in the same sentence as SOX11 in open-access papers (continued):
Sharing a sentence is not in itself a finding about the gene and the disease.
cancer (continued). "The SOX11 gene was found to be altered in only 1.4% of the TCGA pan-cancer dataset." (PMID 36551589, 2022). "Previous studies have shown that the expression levels of SOX11 vary in different cancer types." (PMID 36551589, 2022). "Overall, this study highlights the multifaceted role of SOX11 in a variety of cancers, which may provide a theoretical basis for using SOX11 as a prognostic biomarker in cancer." (PMID 36551589, 2022). "We then detected the protein level of SOX11 using human pan-cancer tissue arrays." (PMID 36551589, 2022). "To date, studies on SOX11 are limited by a single cancer type." (PMID 36551589, 2022). "SOX11 may be a potential biomarker in cancer, as it exhibits aberrantly high expression in a variety of cancers and predicts poor prognosis in cancer patients." (PMID 36551589, 2022). "The main biological processes of SOX11 in cancers were investigated by GSEA." (PMID 36551589, 2022). "Aberrant expression of SOX11 was detected in a total of 27 cancers." (PMID 36551589, 2022). "Next, we further investigated the genomic alterations of SOX11 using the TCGA pan-cancer dataset." (PMID 36551589, 2022). "Regarding the prognostic value of SOX11 in cancer, the available findings are controversial." (PMID 36551589, 2022). "The mRNA level of SOX11 was upregulated in most of the cancer tissues except COAD and READ." (PMID 36551589, 2022). "In addition, SOX11 expression was significantly higher according to the stage of cancer, including BRCA, KIRC, and LUAD, than adjacent normal tissue from TCGA database using the UALCAN." (PMID 34442467, 2021). "SOX11 was identified as a cancer‐suppressor in the progression of different tumors." (PMID 32045135, 2020). "SOX11 expression promotes expression of developmental pathways frequently activated in cancer." (PMID 32909943, 2020). "A significant association of SOX11 and N-CADHERIN (CDH2) expression is also observed in genomic analyses across six cancer types, suggesting that mesenchymal pathways may be activated by SOX11 in both normal and cancer cells." (PMID 32909943, 2020). "Another Sox Group C member, SOX4, shares a similar function to SOX11 in human cancers." (PMID 30922366, 2019). "Our study adds new insights regarding the role of SOX11 in human cancer." (PMID 30922366, 2019). "SOX11 is regarded as a prognostic marker in many different kinds of cancers especially the MCL." (PMID 29113297, 2017). "Finally, we demonstrate that the HDAC inhibitors (vorinostat and trichostatin A) induce SOX11 expression in cancer cells with low levels of SOX11 methylation." (PMID 25880212, 2015). "Sox11’s ability to lower caspases-6, -3, and -7 activities might also be relevant to cancer, since carcinogenesis involves an escape from normal apoptosis." (PMID 26505998, 2015). "Thus, DNA methylation in cancer tissue may be involved in sensitivity to chemoradiotherapy, which suggests SOX11 methylation analysis may be useful to build preoperative treatment strategies for LARC, such as identification of good candidates for NACRT." (PMID 40666491, 2025). "In the light of these promising data, the mechanisms underlying the ability of Sox11 to regulate the pathogenesis of OLP‐associated OSCC were explored in detail, with a particular focus on the processes of acetylation and methylation given their critical importance in several types of cancer." (PMID 39039706, 2024). "Therefore, a systematic investigation the role of SOX11 in cancer is required." (PMID 36551589, 2022). "Moreover, SOX11 plays diverse roles in a variety of types of cancer." (PMID 36551589, 2022). "In addition, GSEA was used to clarify the biological function of SOX11 in pan-cancer." (PMID 36551589, 2022). "It is well known that SOX11 expression may affect the progression of several types of cancers." (PMID 34442467, 2021). "SOX11 overexpression may inhibit gastric tumorigenesis through suppressing cancer cell motility." (PMID 24604109, 2014).
cancer (continued). "Current evidence reveals stark divergence in miR-145s targets across urologic tumors (e.g., SOX11 vs. TAGLN2), underscoring the need for cross-cancer studies to distinguish conserved from context-dependent mechanisms." (PMID 40689207, 2025). "These progenitor cancer cells presented alterations of key transcription factors such as SOX4 (SRY-Box Transcription Factor 4), SOX11 (SRY-Box Transcription Factor 11), and TCF4 (Transcription Factor 4)." (PMID 35875065, 2022). "In this study, we comprehensively explored the expression of SOX11 in normal tissues and its corresponding cancer tissues using the Genotype-Tissue Expression (GTEX) and The Cancer Genome Atlas (TCGA) dataset." (PMID 36551589, 2022). "The expression levels of SOX11 were further investigated for correlation with TMB, MSI and MMR in pan-cancer." (PMID 36551589, 2022). "Among the more than 20 members of the SOX family, SOX11 and SOX4 have been shown to play important roles as targets of mir211 in a variety of cancers." (PMID 35912006, 2022). "The expression of genes related to SOX4, SOX11, and SOX12, which are highly upregulated in various types of cancers, and their related signaling pathways were also examined using a gene meta-analysis database." (PMID 34442467, 2021). "In the present study, we revealed that phylogenetically close SOX members, SOX4, SOX11, and SOX12, have distinctively higher expression in various cancers, and analyzed the prognostic value and correlated pathways using various bioinformatic tools." (PMID 34442467, 2021). "Expression and phylogenetic tree analyses of the SOX gene family revealed that the expression of three closely related SOX members, SOX4, SOX11, and SOX12, was increased in multiple cancers." (PMID 34442467, 2021). "The analysis of SOX4, SOX11, and SOX12 expression revealed that their expression was correlated with patient survival in several types of cancers." (PMID 34442467, 2021). "The majority of the DEGs, e.g., SOX11, TBX21, FAM3B, FGF5, HNF1A, MYB, and PLAC8 have been reported to function as promoters or biomarkers in various cancer types." (PMID 34440579, 2021). "Phylogenetic tree analysis showed that the highly expressed SOX members in various cancers, i.e., SOX4, SOX11, and SOX12, were closely clustered, suggesting similarities in amino acid sequences among these three SOX members." (PMID 34442467, 2021). "Among the genes in the SOX family, the expression of SOX4, SOX9, SOX11, and SOX12 was higher in multiple types of cancers than in their normal counterparts." (PMID 34442467, 2021). "Although it has been reported previously that higher expression of SOX4, SOX11, and SOX12 is negatively correlated with patient survival in various cancers, the expression of SOXC members has not yet been analyzed systematically in multiple cancer datasets." (PMID 34442467, 2021). "Among the groups of SOX family proteins, group C includes three proteins present in most vertebrates: SOX4, SOX11, and SOX126,7; these proteins have been well studied in cancer and in important developmental processes." (PMID 30858360, 2019). "It is usually only expressed in type I GBM cancer stem cells and is co-expressed with the stem cell markers SOX2, SOX11 and OLIG2." (PMID 30208958, 2018). "Three additional predicted cancer driver mutations (EPHA7, MAP3K12, and PCSK5) were identified that were acquired during the transformation of non‐malignant MCF10A cells to malignant DCIS.com cells that could also be implicated in the cell‐context dependency of SOX11 in promoting invasion." (PMID 28707729, 2017). "We have selected five PCGIs (IGF2, SLC16A12, SOX11, P2RX7 and MYOD1) from cancer and inflammation/age related panels." (PMID 27259265, 2016).
cancer (continued). "Upon mapping the list of peptides to genes and referencing those genes for tissue expression levels, we observed several known cancer targets with favorable therapeutic windows, including PHOX2B, PRAME, and SOX11, a primarily developmental transcription factor expressed in many different tumors." (PMID 41477871, 2026). "Although this study demonstrates that miR-127 also downregulates other genes that are overexpressed in cancer, such as FOXO6, SOX11, SOX12, and FASN, it provides the first example that targeting NANOS1 could be a potential cancer treatment strategy." (PMID 36012673, 2022). "SRY-box transcription factor 11 (SOX11), as a member of the SOX family, is a transcription factor involved in the regulation of specific biological processes and has recently been found to be a prognostic marker for certain cancers." (PMID 36551589, 2022). "The functional roles of SOX11 and NGN2 in cancers remain controversial." (PMID 33536579, 2021). "Furthermore, the relative mRNA expression levels of other SOX family members, such as SOX11 and SOX12, are elevated in breast, liver, and lung cancers and have a positive correlation with poor prognosis." (PMID 34442467, 2021). "In addition to regulating the differentiation of epidermal cells, SOX11 and SOX4 also control migration, in line with their reported role in migration in mesenchymal stem cells, neuronal cells, and a variety of cancer cells." (PMID 31492871, 2019). "The silencing mark H3K27me3 was generally present at the SOX11 promoter in non-expressing cells, and an increased enrichment was observed in cancer cells with a low degree of SOX11 methylation compared to cells with dense methylation." (PMID 25880212, 2015). "Cancers of the B-cell lineage are strongly marked by de novo methylation at the SOX11 promoter in SOX11 non-expressing cells, while solid cancer entities display a more varying degree of SOX11 promoter methylation." (PMID 25880212, 2015). "In this case, the association of this cluster of genes with LPHN2 has suggested that LPHN2 may be a regulatory point for the modulation of genes with important roles in cancer, including MMP8 and SOX11." (PMID 21226949, 2011). "Therefore, our analysis may contribute valuable insights into SOX4, SOX11, and SOX12 as a potential therapeutic goal for various human cancers." (PMID 34442467, 2021). "Moreover, IPA analysis shows that OU and Digo could reduce the activity of many transcription factors in which overexpression is required for sustained proliferation and cancer progression (e.g., NRF2, SOX11, TBX2)." (PMID 33352737, 2020). "However, knockdown of SDCCAG8 expression did not significantly alter the expression of SOX11 in the cancer cells." (PMID 30922366, 2019). "Notably, human orthologs of several genes implicated in EMT, TGF-β, and PDGF signaling, which had shown Sox11-dependent expression in TKA-organoids, exhibited highly correlated expression with SOX11 in TCGA samples, indicative of some regulatory relationship among these genes also in human cancer." (PMID 40393982, 2025). "Thus, we suggested that SOX11-mediated pathways in different cancers were not specific." (PMID 36551589, 2022). "Correlations of RMVs between plasma samples and cancer tissues were found for CHFR (|r| = 0.458, p < 0.001), but not for SOX11 (|r| = 0.010, p = 0.94) and CDO1 (|r| = 0.011, p = 0.93)." (PMID 40666491, 2025). "Thus, it is plausible that 2–3 years before the diagnosis of cancer, PCA3-shRNA2 expression is not elevated, as the target mRNAs (such as COPS2 and SOX11) do not have, as yet, altered function in the prostate." (PMID 28380027, 2017).
neurodevelopmental disorder (8 papers, 2016 to 2024). A behavioral and cognitive disorder with onset during the developmental period that involves impaired or aberrant development of intellectual, motor, or social functions. "In contrast, both SOX4 and SOX11 genes within the same C group (SoxC) of the Sox gene family have been associated with neurodevelopmental disorders." (PMID 39057025, 2024). "In conclusion, we describe a series of individuals with SOX11 deletions or de novo mutations presenting a neurodevelopmental disorder, which had clinical features compatible with CSS." (PMID 26543203, 2016). "Our report confirms that SOX11 mutations and deletions can be associated with a neurodevelopmental disorder, which manifests features of CSS." (PMID 26543203, 2016). "Here we further investigate the role of SOX11 variants in neurodevelopmental disorders." (PMID 26543203, 2016).
infection (4 papers, 2010 to 2025). The state of being infected such as from the introduction of a foreign agent such as serum, vaccine, antigenic substance or organism. "The endogenous Gdf5 mRNA level was concomitantly increased in the micromass cultures by the infection of RCAS virus encoding SOX11." (PMID 23356643, 2013). "A similar chondrogenic effect of SOX11 was observed in micromass cell cultures of chick limb bud cells after infection of an RCAS virus encoding human SOX11, as indicated by an increase in Alcian blue staining." (PMID 23356643, 2013). "The observed reductions in Sox2+ and Sox11+ cells highlight a marked impact of maternal infection on early and intermediate stages of neurogenesis in the hippocampus." (PMID 41567998, 2025). "The expression of the four cell proliferation/survival genes (C11ORF82, PGR, SOX11 and HELLS) are significantly reduced when C. burnetii's protein synthesis is inhibited during infection of THP-1 cells." (PMID 20854687, 2010). "The infection efficiency was estimated at around 40% for both the control GFP and NGN2/SOX11 virus." (PMID 25321470, 2014).
neurodegenerative disease (2 papers, 2017 to 2025). A disorder of the central nervous system characterized by gradual and progressive loss of neural tissue and neurologic function. "Overall, the roles of HMGB1, BRD4 and SOX11 as key regulators in the GRN for contrasting DEGs suggests these genes may be key drivers of associated differential alterations in neuroinflammatory, epigenetic and adult neurogenesis-related processes in neurodegenerative diseases." (PMID 41318503, 2025).
neurological diseases (2 papers, 2010 to 2024). "The knockdown of Sox11 level influences neuroinflammation and the death of cells in various neurological diseases." (PMID 38800035, 2024). "SOX11 is suggested to function in the developing nervous system while lack of glial fibrillary acidic protein (GFAP) gene function in knock-out mice increases the outgrowth of axons from neurons of the spinal cord (GFAP is central in an IPA cluster related to neurological disorders." (PMID 21042590, 2010).
hematological malignancies (1 paper, 2018). "Interestingly, all 5 RNA samples harvested from patients in CR of their hematological malignancies and CCND1 positive at diagnosis were categorized at low level of SOX11 expression." (PMID 29484276, 2018).
musculoskeletal diseases (1 paper, 2017). "To date, only a few studies have reported the dysregulation of SOX11 in human musculoskeletal diseases." (PMID 29371932, 2017).
SOX11 also shares sentences with these, for which no sentence is quoted: acute lymphoblastic leukemia (4 papers); hairy cell leukemia (4); neuroendocrine tumours (4); adenocarcinoma (3); brain tumors (3); adenopathy (2); aniridia (2); brain cancer (2); growth deficiency (2); Hirsutism (2); MALT lymphoma (2); pheochromocytoma (2); sarcoma (2); T-cell prolymphocytic leukemia (2); ablepharon macrostomia syndrome (1); Alzheimer disease (1); anemia (1); Anophthalmia (1); appendiceal lymphomas (1); astrocytomas (1); autism (1); autism spectrum disorder (1); B-cell precursor acute lymphoblastic leukemia (1); Barber-Say syndrome (1); basal cell carcinoma (1); bipolar disorder (1); brain disease (1); brain injury (1); breast (1); campomelic dysplasia (1).
A further 72 diseases each share a sentence with SOX11 in 1 paper.